LINC00351 (long independently transcribed non-coding RNA 351)
Gene: Long non-coding RNA gene on chromosome 13 (85,363,601 to 85,544,570, forward strand). Ensembl gene ENSG00000226317.
Diseases named in the same sentence as LINC00351 in open-access papers:
LINC00351 is named in the same sentence as 1 disease in open-access papers, as found by Europe PMC text mining. Sharing a sentence is not in itself a finding about the gene and the disease. The quoted sentences say what the papers report.
amyotrophic lateral sclerosis (1 paper, 2019). Amyotrophic lateral sclerosis (ALS) is a neurodegenerative disease characterized by progressive muscular paralysis reflecting degeneration of motor neurons in the primary motor cortex, corticospinal tracts, brainstem and spinal cord. "One of the top ranked genetic associations for this cluster (rs76548985, p-value=1.43e-06) is LINC00351, associated with sporadic amyotrophic lateral sclerosis." (PMID 31818369, 2019).